COMP (cartilage oligomeric matrix protein)
Diseases named in the same sentence as COMP in open-access papers (continued):
Sharing a sentence is not in itself a finding about the gene and the disease.
myocardial infarction (5 papers, 2018 to 2023). Gross necrosis of the myocardium, as a result of interruption of the blood supply to the area, as in coronary thrombosis. "However, high levels of COMP were found to be associated with a lower risk of incident myocardial infarction in a case–control study." (PMID 31963737, 2020). "Fibroblasts from GA patient 2 (sub-cluster 7), meanwhile, expressed elevated amounts of SPOCK1 (Avg-Log FC: 0.99), CRLF1 (Avg-Log FC: 1.38), and COMP (Avg-Log FC: 1.35), a cartilage protein that is upregulated in matrix-producing fibroblasts after myocardial infarction." (PMID 33053333, 2020). "Therefore, it was suspected that the decrease in COMP levels after myocardial infarction promoted ventricular dilatation." (PMID 29523183, 2018).
ovarian carcinoma (5 papers, 2015 to 2025). A malignant neoplasm originating from the surface ovarian epithelium. "Immunohistochemical analyses showed varying degrees of COMP expression in ovarian cancer tissues, with high COMP expression in the stroma being strongly associated with decreased OS of ovarian cancer patients (p < 0.001)." (PMID 38615020, 2024). "Consistently, in the present study, Notch dependency of the migration and tumorspheres formation induced by COMP in ovarian cancer cells was observed." (PMID 38615020, 2024). "This study investigated COMP’s role in ovarian cancer, exploring clinicopathological links and mechanistic insights." (PMID 38615020, 2024). "This study suggests that COMP secretion by CAFs drives ovarian cancer progression through the induction of the Notch pathway and epithelial-to-mesenchymal transition." (PMID 38615020, 2024). "These compelling observations show that COMP selectively activates the Notch3 signaling pathway in ovarian cancer cells." (PMID 38615020, 2024). "In this study, we identified a significant correlation between increased COMP expression in tumor stroma and shorter OS in ovarian cancer patients." (PMID 38615020, 2024). "The dependency of the COMP effect on Notch was confirmed when the migration and tumorsphere formation of COMP-treated ovarian cancer cells were inhibited upon incubation with Notch inhibitors." (PMID 38615020, 2024). "Consistently, mice co-transplanted with COMP-expressing CAFs and ovarian cancer cells exhibited considerably larger tumors and a higher frequency of lung metastases compared to the control group co-transplanted with mock CAFs and ovarian cancer cells." (PMID 38615020, 2024). "The effect of recombinant COMP on the CSCs population of ovarian cancer cell lines was assessed by the tumor sphere formation assay." (PMID 38615020, 2024). "To study COMP’s mechanism of action, we used purified recombinant COMP and observed a dose-dependent binding of COMP to ovarian cancer cells, which enhanced their migration and invasion capabilities." (PMID 38615020, 2024). "The results revealed a higher number of spots per cell in COMP-treated ovarian cancer cells compared to the control group, indicating an increased interaction of Notch3 and Jagged1 in the presence of COMP." (PMID 38615020, 2024). "Consistently, COMP secreted by COMP-expressing 3T3 cells (mouse fibroblasts) significantly increased the migration ability of ID8 cells (mouse ovarian cancer cell line) compared with the control." (PMID 38615020, 2024). "RT-qPCR array for EMT-specific genes showed that the expression of seventeen genes was significantly changed in both ovarian cancer cell lines upon stimulation with COMP." (PMID 38615020, 2024). "Herein, a similar observation was made for ovarian cancer cells treated with recombinant COMP using tumorsphere formation assay." (PMID 38615020, 2024). "To evaluate the potential protective role of recombinant COMP against apoptosis, through binding to the cell surface, in ovarian cancer cells, we conducted an Annexin V-Zombie aqua dye apoptosis assay, with cisplatin serving as the apoptosis inducer." (PMID 38615020, 2024). "The migration ability of ovarian cancer cell lines, SKOV3 and OAW42, co-cultured with the COMP-expressing CAFs, was increased compared to the same ovarian cancer cell lines co-cultured with the mock CAFs." (PMID 38615020, 2024). "To further assess the paracrine effect of COMP on ovarian cancer cells, we first evaluated the binding capability of recombinantly expressed and purified COMP to ovarian cancer cell lines." (PMID 38615020, 2024). "A significant increase in ALDH-positive ovarian cancer cells was observed when cells were exposed to recombinant COMP for 48 h." (PMID 38615020, 2024). "Our results showed that SNHG25 facilitated the proliferation, migration and invasion of ovarian cancer cells via regulating COMP expression." (PMID 33613753, 2021).
ovarian carcinoma (continued). "In vitro and in vivo findings demonstrated that SNHG25 promotes the proliferation, invasion and metastasis of ovarian cancer cells, potentially by regulating COMP." (PMID 33613753, 2021). "The present study demonstrated a significant decrease in the expression of COMP protein in SNHG25 knockdown compared to control ovarian cancer cells in vitro." (PMID 33613753, 2021). "However, the mechanism of action of COMP and its clinical correlation with ovarian cancer remains unexplored." (PMID 38615020, 2024). "Therefore, in alignment with the in vivo observations, these results emphasize the substantial paracrine influence of COMP-expressing CAFs on promoting ovarian cancer cells’ metastatic ability." (PMID 38615020, 2024). "Indeed, given the Notch3 activation by COMP, we subsequently observed EMT induction in ovarian cancer cells following COMP treatment." (PMID 38615020, 2024). "Therefore, our study aimed to explore the potential links between COMP and clinicopathological characteristics of epithelial ovarian cancer and to unravel the mechanism by which COMP is driving the progression of ovarian cancer." (PMID 38615020, 2024). "Functionally, secreted COMP by CAFs enhanced the migratory capacity of ovarian cancer cells." (PMID 38615020, 2024). "Based on immunohistochemical analysis of epithelial ovarian tumor tissues, COMP expression in the stroma, but not in cancer cells, was linked to worse overall survival (OS) of ovarian cancer patients." (PMID 38615020, 2024). "Moreover, COMP treatment induced epithelial-to-mesenchymal transition and upregulation of active β-catenin in ovarian cancer cells." (PMID 38615020, 2024). "Furthermore, the expression of COMP in the stroma could serve as a promising prognostic indicator for ovarian cancer patients." (PMID 38615020, 2024). "The discovery of a link between stromal COMP and adverse clinical outcomes motivated us to investigate how stromal COMP in the TME influences ovarian cancer cells, which might provide crucial insights into the mechanisms underlying ovarian cancer progression and metastasis." (PMID 38615020, 2024). "Therefore, we hypothesized that the paracrine effect of COMP on increasing the metastatic potential of ovarian cancer cells, observed in vivo, is mediated by the induction of EMT in ovarian cancer cells." (PMID 38615020, 2024). "However, the involvement of COMP in ovarian cancer remains to be elucidated." (PMID 33613753, 2021). "Larger tumor spheres were formed by ovarian cancer cell lines, SKOV3 and OAW42, treated with recombinant COMP in a dose-dependent manner compared with control cells." (PMID 38615020, 2024). "The activation of Notch3 is not limited to COMP but can also be achieved by other TSP family members, such as TSP2 function in lung and ovarian cancer cells." (PMID 38615020, 2024). "In vivo and in vitro experiments confirmed the paracrine role of COMP secreted by CAFs, potentially upregulated by TGF-βs, in driving the ovarian cancer cells’ aggressiveness." (PMID 38615020, 2024). "Transwell migration assays indicated that COMP-induced migration was significantly reduced by DAPT (10 μM) and the anti-Jagged1 antibody (5 μg/ml) in both ovarian cancer cell lines." (PMID 38615020, 2024). "High-throughput sequencing and western blot analysis showed a significant decrease in the expression of COMP mRNA and protein in SNHG25 knockdown compared to control ovarian cancer cells." (PMID 33613753, 2021). "While COMP has roles in ECM stabilization through interactions with collagen in normal tissue development, a few studies have recently emerged showing COMP also has roles in tumor development in a number of cancers, including prostate and ovarian cancer." (PMID 41009743, 2025). "The results demonstrated that exposing the cisplatin-treated cells to recombinant COMP did not alter the number of apoptotic cells, suggesting that cell membrane-bound COMP does not confer protection against apoptosis in ovarian cancer cells." (PMID 38615020, 2024).
ovarian carcinoma (continued). "Moreover, in the present study, we found that the extracellular COMP did not protect ovarian cancer cells from apoptosis." (PMID 38615020, 2024). "Since COMP did not affect the proliferation and apoptosis of ovarian cancer cells, we hypothesized that the larger primary tumors in mice co-injected with COMP-expressing CAFs observed in vivo might be due to the COMP effect on CSCs expansion." (PMID 38615020, 2024).
aortic aneurysm (4 papers, 2020 to 2024). A ruptured aneurysm located in the wall of the proximal portion of the descending aorta proceeding from the arch of the aorta. "Human studies also show that COMP downregulation is associated with aortic aneurysm." (PMID 36012514, 2022). "Aortic aneurysm in COMP−/− mice could be rescued by the application of a peptidomimetic that mimics the AT1-binding motif of COMP." (PMID 36012514, 2022). "COMP supplementation is a promising treatment for OA and aortic aneurysms while it may induce tissue fibrosis or cancer metastasis." (PMID 36012514, 2022). "Most recently, tPVAT-derived cartilage oligomeric matrix protein (COMP) has been reported to suppress VSMC apoptosis and to attenuate aortic aneurysm formation in mice." (PMID 39156105, 2024). "Human aortic aneurysm induction is related to upregulated ADAMTS-7 and downregulated COMP in the ADAMTS7/COMP pathway." (PMID 32095376, 2020).
breast tumors (4 papers, 2010 to 2024). "A xenograft orthotopic breast tumor model was established to assess whether COMP may promote chemoresistance in vivo." (PMID 38965233, 2024). "One possible explanation for this observation may be that in order to yield detectable levels of COMP in serum, the breast tumors must locally express high quantities of COMP, which is then strongly correlated with late stage disease and worse prognosis." (PMID 31737569, 2019).
Cirrhosis (4 papers, 2018 to 2022). A chronic disorder of the liver in which liver tissue becomes scarred and is partially replaced by regenerative nodules and fibrotic tissue resulting in loss of liver function. "The current study aimed to evaluate serum COMP as a diagnostic marker for HCC in patients with cirrhosis and to correlate it with other parameters of disease progression." (PMID 35845304, 2022). "The current study purposed to evaluate serum COMP (Cartilage oligomeric matrix protein) as a diagnostic marker for HCC in patients with cirrhosis and to correlate it with other parameters of disease progression." (PMID 35845304, 2022). "Positivity for both markers was associated with cirrhosis [23/24 (95.8%) for GP73(+)/COMP(+) vs. 22/30 (73.3%) for GP73(+)/COMP(−) vs. 25/37 (67.6%) for GP73(−)/COMP(+) vs. 46/197 (23.4%) for GP73(−)/COMP(−); P < 0.001]." (PMID 34298722, 2021). "Our study showed that dual positivity for GP73 and COMP is strongly associated with the presence of significant fibrosis and cirrhosis." (PMID 34298722, 2021). "Although the presence of cirrhosis is clearly associated with an increased risk of disease progression, the detection of COMP in cirrhotic patients is a potentially useful marker to identify a subgroup of cirrhotic patients with a higher likelihood of developing HCC." (PMID 35845304, 2022). "COMP is largely found in the extracellular matrix protein of skeletal tissue, but increased COMP expression has been also associated with fibrogenesis in patients with cirrhosis and HCC." (PMID 34298722, 2021). "Next, a clinicopathological association analysis in the 100 HCCs found that the high-level of serum COMP was closely associated with poor clinicopathological features, including cirrhosis (P = 0.013), vascular invasion (P = 0.031), large tumor size (P = 0.020) and tumor recurrence (P = 0.043)." (PMID 30231922, 2018). "Several publications have revealed that COMP is involved with the process of cirrhosis and HCC progression." (PMID 35845304, 2022). "In conclusion, the combination of GP73 and COMP seems efficient to detect cirrhosis and predict worse outcomes and the development of HCC in patients with chronic liver diseases." (PMID 34298722, 2021). "Dual positivity for GP73 and COMP had a high discriminative ability for detecting cirrhosis [AUC (95% CI): 0.882 (0.839–0.917)]." (PMID 34298722, 2021). "We confirmed, in a large cohort of 288 patients with chronic liver diseases, that the combination of GP73 and COMP had a high discriminative ability to detect severe fibrosis/cirrhosis and is efficient in predicting the development of HCC." (PMID 34298722, 2021). "Analyses using univariate Cox regression indicated that tumor size, cirrhosis, vascular invasion and high serum COMP level were all found to be significantly related with overall survival (P < 0.05)." (PMID 30231922, 2018). "Of note, the combined positivity for GP73 and COMP were associated with the presence of cirrhosis at baseline; 23/24 (95.8%) for GP73(+)/COMP(+) vs. 22/30 (73.3%) for GP73(+)/COMP(−) vs. 25/37 (67.6%) for GP73(−)/COMP(+) vs. 46/197 (23.4%) for GP73(−)/COMP(−) (P < 0.001)." (PMID 34298722, 2021). "From clinical data, we concluded that COMP level was closely correlated with cirrhosis and HCC, therefore we designed experiments to detect whether the main source of COMP was from HSCs." (PMID 30231922, 2018). "Several publications revealed that COMP was involved with process of cirrhosis and HCC progression." (PMID 30231922, 2018). "The current study demonstrated a positive correlation between COMP and fibrosis indices (APRI and FIB-4) in both the HCC and the cirrhosis groups." (PMID 35845304, 2022). "Moreover, the combination of COMP and GP73 showed a pronounced performance in detecting severe fibrosis/cirrhosis and predicting the development of HCC in patients with chronic liver diseases." (PMID 36012514, 2022).
Cirrhosis (continued). "Notably, most patients with dual positivity for COMP and GP73 had cirrhosis, while in the subgroup analysis of patients with available liver biopsy, all patients who tested positive for both biomarkers had significant fibrosis." (PMID 34298722, 2021). "In contrast, patients with positivity for both GP73 and COMP who were followed for more than 6 months had significantly higher rates of HCC development either in the total patients’ group (n = 229; P < 0.001) or in those with established cirrhosis at baseline (n = 82; P < 0.001)." (PMID 34298722, 2021). "The development of cirrhosis was not different in GP73(+)/COMP(+), GP73(+)/COMP(−), GP73(−)/COMP(+), and GP73(−)/COMP(−) patients (Kaplan-Meier analysis; P = 0.589)." (PMID 34298722, 2021).
COVID-19 (4 papers, 2021 to 2025). A disease caused by infection with severe acute respiratory syndrome coronavirus 2. "COVID-19 is associated with decreased COMP and osteocalcin levels, indicating cartilage degradation and impaired bone formation, alongside elevated HA, ALP, PINP, OPN, and MMPs, reflecting increased joint inflammation, bone remodeling, and tissue breakdown." (PMID 40943488, 2025). "Individuals who have been diagnosed with COVID-19 have been shown to have decreased serum COMP levels." (PMID 40943488, 2025). "The identification of altered biomarkers such as osteocalcin, PINP, ALP, OPN, COMP, HA, IGF-1, myostatin, follistatin, and creatine kinase can provide a foundation for developing minimally invasive diagnostic tools to detect early bone, cartilage, and muscle involvement in COVID-19 patients." (PMID 40943488, 2025). "Biomarkers such as cartilage oligomeric matrix protein (COMP), hyaluronic acid (HA), osteocalcin, and procollagen type I N-terminal peptide (PINP) have been identified as key indicators of musculoskeletal health and are notably affected in COVID-19 patients." (PMID 40943488, 2025). "Interestingly, thrombospondin-5 (cartilage oligomeric matrix protein, COMP), which is essential to maintain a contractile / differentiated phenotype of vascular smooth muscle cells (VSMC) under physiological and pathological stimuli, was up-regulated during recovery from COVID-19." (PMID 39183264, 2024).
cyst (4 papers, 2019 to 2025). A sac-like closed membranous structure that may be empty or contain fluid or amorphous material. "The ultrastructure of in vitro CST2-HA, KO, and COMP cysts were examined by electron microscopy to further assess the role of CST2 in cyst morphology." (PMID 31040239, 2019). "A detailed review of the seven subjects with low COMP/IL‐8 ratios in terms of demographic, age, or other observations showed that one patient presented with a Baker's cyst, which was drained in conjunction with the joint aspiration, likely contributing to the elevated IL‐8." (PMID 39690934, 2025).
diabetes (4 papers, 2012 to 2025). "In this line, COMP-Ang-1, a new developed soluble and stabile form of Ang-1, has been shown to prevent the diabetes related retinopathy and nephropathy." (PMID 22412941, 2012). "Furthermore, COMP-Angpt1 and podocyte-specific overexpression of Angpt1 had renoprotective roles in diabetes." (PMID 29293543, 2018). "COMP-Angpt1 and podocyte-specific overexpression of Angpt1 had renoprotective roles in diabetes." (PMID 29293543, 2018).
gastric cancer (4 papers, 2020 to 2025). A primary or metastatic malignant neoplasm involving the stomach. "Gastric cancer is the world’s third leading cause of cancer deaths, and COMP is significantly elevated in gastric cancer, leading to its proposal as a prognostic marker for this condition." (PMID 41009743, 2025). "In gastric cancer (GC), tumor COMP has also been identified as a diagnostic and prognostic biomarker." (PMID 36012514, 2022). "COMP has been proposed as a prognostic biomarker and potential therapeutic target for the treatment of gastric cancer." (PMID 41009743, 2025).
heart failure (4 papers, 2018 to 2024). Inability of the heart to pump blood at an adequate rate to meet tissue metabolic requirements. "Our results suggest that COMP, COL8A1, LOX, and ACOT1 warrant further investigation in the development of cardiac fibrosis and as potential biomarkers for causing heart failure." (PMID 38854759, 2024). "Whether the COMP–prohibitin 2 interaction in the heart plays essential roles in mitochondrial function and heart failure requires further investigation." (PMID 29867124, 2018). "Overexpression of lysine-specific demethylase 3A (KDM3A) leads to the up regulation of fibrosis-related genes COMP, COL8A1, and LOX and the down regulation of ACOT1, result in enhanced fibrosis and heart failure." (PMID 38854759, 2024).
liver cirrhosis (4 papers, 2018 to 2025). "Recent studies have found that COMP binds to CD36 and activates downstream signaling pathways and ultimately leading to the progression of liver cirrhosis." (PMID 30231922, 2018). "Earlier work has suggested that COMP levels in the serum of HCC patients and HCC tissues are abnormally elevated compared with healthy controls and it can be used as diagnostically in the non-invasive estimation of liver cirrhosis and HCC development." (PMID 30231922, 2018).